CCL4 (C-C motif chemokine ligand 4)
Diseases named in the same sentence as CCL4 in open-access papers (continued):
Sharing a sentence is not in itself a finding about the gene and the disease.
infection (continued). "Microglia also express additional subsets of chemokines (Ccl2, Ccl3, Ccl4) with no overlap to those detected in vascular-associated cells, potentially indicating non-redundant mechanisms of T cell recruitment into the brain parenchyma during infection." (PMID 36180478, 2022). "Furthermore, we could only identify a trend or correlation between levels of IL-1β expression and those of IL-6, CCL3 and CCL4 in the very early infection phase (3 h) and at high bacterial loads (MOI = 1:1000)." (PMID 33652921, 2021). "At times early following infection, multiple transcripts encoding proinflammatory molecules were increased, including IL8 (8196-fold), IL1B (1559-fold), oncostatin M (OSM, 799-fold), CCR1 (588-fold), CXCR1 (625-fold), CXCR2 (596-fold), CCL4 (514-fold), and CCL3 (658-fold)." (PMID 25719526, 2015). "Infection of rhesus (Macaca mulatta) or cynomolgus (Macaca fascicularis) macaques with pathogenic SIV leads to the induction of multiple inflammatory chemokines in lymph nodes and spleen including: CXCL8; CXCL9, CXCL10, and CXCL11; CCL3, CCL4, CCL5; CCL2; CCL19; and CCL20." (PMID 19149556, 2009). "In urine, we found increases in IL-1RA, G-CSF, and chemokines CXCL10, CCL4, CCL11, GROα/β/γ, and IL-8/CXCL8, with IL-1RA and CCL4 showing direct correlation with the degree of pyuria at the time of infection." (PMID 41810365, 2026). "Secreted CCL3, CCL4, CCL5, CXCL10, IFN-γ, IL-10, and VEGF were also significantly elevated in LCLs but at lower levels than in de novo infection." (PMID 40359016, 2025). "Like PMs, THP-1 cells also produced IL-6, CCL4, CCL2, IL-1RA, CCL3, and CXCL9 upon infection with the RSV strain A-0594, although the peak of these responses differed in some cases." (PMID 41280933, 2025). "For this, we measured the quantity of CCL3, CCL5, and CCL4 in the culture supernatants of macrophages infected with HIV and treated with P3DEX or DEX at 24, 48, and 72 h post infection." (PMID 40077760, 2025). "This pattern resembles the cytokine-mediated induction reported during Mab infection of THP-1 macrophages, which led to elevated expression of TNF-α, CCL4, IL-8, and IL-1β." (PMID 40762982, 2025). "Post-infection, CF7066 significantly upregulated the transcriptional expression of inflammatory factors such as CCL4, IL-6, IL-8, and TNF-α, exhibiting the highest mRNA levels." (PMID 40793820, 2025). "In neonatal Swiss mice, USUV infection led to an increase in typical neuroinflammatory cytokines, including IL-6, CCL3, CCL4, CCL5, CXCL9, and CXCL10, with CXCL10 being upregulated to the highest level in this model." (PMID 39907280, 2025). "We found that infection of PBMC by the neurovirulent HIV-1ADA and treatment of PBMC by recombinant Tat of HIV-1YU-2 strain, both up-regulated chemokines CCL-2, CCL-3, and CCL-4 to significant levels." (PMID 40313367, 2025). "Compared to “transient” CD8 T cells, the “durable” CD8 T cells upregulated the expression of chemokines such as CCL4 and CCL5, which attract immune cells to the site of infection, as well as cytotoxic protein marker NKG7." (PMID 38561339, 2024). "By bonding with particular chemokines, such as CCL3, CCL4, CCL5, CCR1 facilitates cell chemotaxis, directing immune cell migration towards inflammatory or infection sites, a function vital for initiating and modulating immune responses." (PMID 39931101, 2024). "Chemokines (CCL2, CCL3L1, CCL4, CXCL9, CXCL10, CXCL11, and XCL1) were also significantly upregulated after infection." (PMID 38698849, 2024). "Significant decreases in CCL3, CCL4, and CXCL2 were observed in the galea of TNF KO mice at day 14 post-infection, corresponding to the timepoint and anatomical location where granulocyte recruitment was maximally reduced." (PMID 39044282, 2024). "We observed that concentrations of the monocyte chemoattractants CCL2, CCL3, CCL4, CCL5, and CCL7 were significantly increased in mice inoculated with both pathogens, relative to vehicle and single Bb infection." (PMID 39229265, 2024).
infection (continued). "Cytokine analysis indicated CCL5 (RANTES), CXCL9 (MIG), CCL4 (MIP-1B), and IFN-y peak between day 1 and 2 post infection dependent on the route of infection." (PMID 39734493, 2024). "Upon infection with influenza viruses, CCR5 and its cognate chemokines CCL3, CCL4, and CCL5 are induced rapidly, which contributes to leukocyte recruitment into the airways and a consequent efficacious antiviral response." (PMID 37041527, 2023). "Conversely, on day 7 after infection, the levels of MCP-1 and CCL4 were higher in WT-infected mice than in ΔPbMAP1-infected mice." (PMID 37563696, 2023). "Compared to B lineage isolates, infection of mice with UT21 had lower levels of CCL2, CCL3, CCL4, TNF-α, and IL-1β." (PMID 36992320, 2023). "The expressions of CCR5 (the receptor of CCL3, CCL4, and CCL5) and CCRL2 (expressed on neutrophils and primary monocytes) were significantly down-regulated by the WT infection." (PMID 37513744, 2023). "Before infection, the latent condition presented the chemokine panel with near-high levels of CXCL11 and mild or moderate levels of CXCL2, CCL4, CCL2, CCL1, and CXCL9." (PMID 37149713, 2023). "Infection with this bacterium was shown to increase the production of IFN-γ, TNF-α, and chemokines such as CCL3, CCL4, CCL5, CCL11, and CXCL1." (PMID 38139161, 2023). "Macrophage inflammatory proteins are also known as chemotactic cytokines that comprise CCL4 and CCL20, which play an important role in coordinating the host’s immune responses against infection." (PMID 37237892, 2023). "We have previously suggested that NK cells do not have a role in the direct control of the mycobacteria growth of Mtb, however, the contact between NKs and DCs during infection by M. bovis increases the production of IFN-γ, TNF-α, CCL2, CCL4, and CXCL8." (PMID 35456728, 2022). "ELISA analysis of supernatants confirmed that VACV∆C7L infection resulted in the secretion of IFN-β, CCL4 and CCL5 from WT AECIIs." (PMID 35351885, 2022). "We confirmed a MDA5/STING-dependent upregulation of cytokine and chemokine genes after VACV∆C7L infection in AECII cells, including Ifnb1, Ccl2, Ccl7, Ccl4, Ccl5, and Cxcl10." (PMID 35351885, 2022). "The proteomics and Luminex data showed that various macrophage and neutrophil related cytokines and chemokines like MCP-1, IP-10 (CXCL10), MIG, MIP-1β (CCL4), CXCL8 (IL-8), SAA2, and AXL were dramatically upregulated at 7 days after infection." (PMID 35903092, 2022). "Transcripts encoding cytokines and chemokines such as IL-1β (interleukin-1β), IL-18, IL-6, IFN-γ, IL-10, CCL2 (C-C motif chemokine ligand 2), CCL4 and CCL7 were also up-regulated in the lungs during infection." (PMID 34965194, 2022). "The anti-inflammatory genes CCL4 and EBI3 were induced earlier (5 dpi) upon infection with the wt isolate." (PMID 35215144, 2022). "In WT lung epithelial cells, infection with VACV∆C7L induced higher expression levels of Ifnb1, Ccl4, and Ccl5 compared with WT VACV." (PMID 35351885, 2022). "Lenti-Spike infection significantly increased the expression of inflammatory cytokines, including IL-1β, IL-6, and TNF-α, and chemokines, including CCL-2, CCL-3, CCL-4, and CXCL-10, whereas Lipo-hACE2 decoy significantly inhibited all these effects." (PMID 35401811, 2022). "Various inflammatory cytokines such as TNF (TNF), some ILs (IL1α, IL1β), and chemokines (including CCL2, CCL4, CCL5, CXCL8) were significantly up-regulated under all observation points after YC-2020 infection." (PMID 36338035, 2022). "Remarkably, the knockdown of Nbeal2 significantly promoted the production of IL-1α, IP-10, IL-6, CCL-4 and TNF-α at 24 h post-infection in P815 cells infected with H1N1 virus and H5N1 virus." (PMID 35215885, 2022). "In tissues treated prior to infection, baseline production of IL-1β, IL-22, CCL3, CCL4 and CCL5 varied between BaL- and LAI-infected explants, possibly reflecting virus difference in cell tropism and subsequent CD4 T cell depletion." (PMID 34835109, 2021).
infection (continued). "VSV infection significantly induced the expression of seven chemokines (CCL3, CCL4, CCL5, CCL20, CXCL1, CXCL2, and CXCL3) by ~3- to 42-fold compared to mock infection." (PMID 34578166, 2021). "Those that were significantly higher in the vehicle mice at the late stage of infection included the monocyte and neutrophil chemoattractants CCL2, CCL4, and MIP-2a." (PMID 34835277, 2021). "For example, Ebola virus (EBOV) infection of monocytes results in strong induction of inflammatory cytokines including IL-6, IL-8, and chemokines CCL3/MIP-1a and CCL4/MIP-1b, with downregulation of class II MHC expression." (PMID 34239884, 2021). "Several chemokines were induced quickly in the early phase (day 2 p.i.)and maintained at a rather high level through the first week of infection, including CCL2, CCL3, CCL4, CCL7, CXCL10, IL-6, IFN-γ, CCL11, CCL5, TNF-α, CXCL1, IL-4, IL-12p70." (PMID 34379705, 2021). "Upon infection with influenza virus, production of cytokines and chemokines including CCL3, CCL4, and CCL5 from respiratory epithelium recruits γδ T cells at the site of infection in a CCR5 receptor-dependent fashion." (PMID 33183352, 2020). "We found that ex vivo infection of whole blood with MVA significantly induced the production of IL-8, CCL2, and CCL4 in monocytes and HLA-DRhigh DCs of HIV-ART patients and healthy persons." (PMID 33013882, 2020). "pDCs are capable of producing various chemokines such as CCL4, CCL5, and CXCL10, which attract T cells to sites of infection and inflammation." (PMID 30984181, 2019). "Then we further demonstrated that autophagy blocked the production of the cytokines IL-8, CCL4, and CCL5 induced by SH0165 infection through the inhibition of NF-κB, p38, and JNK MAPK signaling pathway." (PMID 31106159, 2019). "For instance, Th1 cells express high levels of CCR5 but also produce MIP-1α (CCL3), MIP-1β (CCL4) and RANTES (regulated upon activation normal T-cell expressed and secreted) (CCL5), the natural ligands for CCR5, thereby limiting R5 infection in these cultures." (PMID 31487324, 2019). "Since infection-primed ADAPko NK cells exhibited impaired production of the phagocyte attracting chemokines CCL3, CCL4, and CCL5 we compared the number of monocytes and neutrophils in the spleen of Lm infected animals." (PMID 32038647, 2019). "The protein levels of CCL2, CCL3, CCL4, and CCL5 in the liver of μMT mice 6 weeks after infection were significantly increased compared with those of WT mice." (PMID 31194740, 2019). "The infection of sham-operated mice with MCMV resulted in the induction of a different chemokine subset containing Ccl12, Ccl7, Ccl4 and Cxcl10." (PMID 29953538, 2018). "Infection with the ΔgliP mutant significantly stimulated the expression of CXCL2, CCL3, CCL4, CCL7, TNF-α, and IL-6, whereas infection with the Δaspf1 ΔgliP double mutant significantly decreased the expression of CXCL2, CCL7, TNF-α, and IL-6." (PMID 30052103, 2018). "Further, although we did not observe significant differences in monocyte recruitment to the footpad, CCL3, CCL4, CCL7, and CXCL10 are all known monocyte chemoattractants that were also significantly reduced during Opal524R infection." (PMID 29138302, 2017). "Optimal expression of Ccl2, Ccl3, Ccl4, and Cxcl1 depends on DDR signaling in macrophages, and these chemokines regulate the migration of innate immune cells during infection." (PMID 28362262, 2017). "We found mRNAs of the type 1 chemokine ligands and their receptors (CCL4, CCL5, CCR5, CXCL9, CXCL10, CXCL11 and CXCR3) were increased at 21–28 days post-infection compared to uninfected controls." (PMID 28103263, 2017). "The production of CXCL10, CCL4 and CCL5 was markedly increased by HAV (HM-175/18f) infection in the culture of primary human hepatocytes and HepG2 cells." (PMID 28744018, 2017). "Another network centered on chemokines (CCL2 and CCL4) and IFN-γ also supports a role for cell recruitment and immunity in infection." (PMID 26214306, 2015).
infection (continued). "The expression of chemokines CCL3, CCL4 and CCL5 was reported during the acute and chronic stages of infection by T. cruzi." (PMID 26599761, 2015). "The results showed that PAMs infected with M. hyopneumoniae exhibited significantly increased expression of CCL4, CXCL2 and CXCL10 mRNA at 6 h post-infection, and decreased at a steady-state level, with maximal production at 6 h post-infection." (PMID 25098731, 2014). "In this context, there is a marked induction of CCL2, CCL3, CCL4, CCL5, CXCL8, and CXCL10 after infection with SIV, as well as a systemic increase of CCL2, CXCL8, and CXCL10 in humans, concurrently with viremia peak after infection with HIV." (PMID 25313360, 2014). "Studies demonstrating the contribution of T cells to disease pathogenesis, suggest the recruitment of T cells by chemokines (CCL4 and CCL8) elicited at the site of infection would most likely contribute to the pathogenesis of mycoplasma disease." (PMID 25098731, 2014). "IEC isolated from neonates at the peak of the infection presented a clear up-regulation of XCL1, CCL3, CCL4, CCL5, CXCL9, and CXCL10 expression, with levels close to those in adults for CXCL9 and CXCL10." (PMID 24367259, 2013). "Those mRNAs for CCL2, CCL31, CCL4, CXCL10, CCR1 and CCR5 were significantly increased following infection in both experiments in at least one time-point and CCL5, CCR9 and CXCR4 mRNA were significantly altered in one of the experiments." (PMID 24083897, 2013). "Levels of mRNAs for CCL2, CCL3L1, CCL4, CXCL10, CCR1 and CCR5 were significantly increased in at least one time point following infection in two experiments and CCL5, CCR9 and CXCR4 mRNA were significantly increased in one of the experiments." (PMID 24083897, 2013). "Addition of Bb induced up-regulation of transcript levels for all chemokines assessed, including CXCL1, CXCL2, CCL2, CCL3, CCL4, and CCL5 by MØs and DCs as early as 4h post-infection." (PMID 24367705, 2013). "An up-regulation of Ccl3, Ccl4, Ccl5, and Tgfb, a strong CD4+ T-cell response, and down-regulation of Il17, Il21 and Il23 occurred during infection." (PMID 23383148, 2013). "Elevated levels of CCL3, CCL4, CCL5 and CXCL9 mRNA were detected in the livers of both WT and WSX-1−/− mice on day 7 of infection, whereas CCL3, CCL4, CCL5 and CCL20 mRNA levels were increased on day 14 of infection." (PMID 24244314, 2013). "Accordingly, IEC isolated from IFNγ−/− neonatal mice did not significantly upregulate the expression of CXCL9 and CXCL10 during the infection whereas other chemokines such as CCL3, CCL4 and CCL5 were still upregulated." (PMID 24367259, 2013). "CBMC production of CCL4 and CXCL10 was near maximum at 12 hours and was still detected at 48 hours post-infection." (PMID 22479521, 2012). "Time course analysis revealed that primary human CBMCs accumulate maximal levels of CCL4 and CXCL10 mRNA and produce CCL4 and CXCL10 in nanogram amounts as early as 12 hours post-infection." (PMID 22479521, 2012). "The expression of CCL chemokine ligands CCL2, CCL4 and CCL7 was significantly higher in cells infected with the mutant, relative to the cells infected with Mtb, immediately following infection at the 0 hr time-point." (PMID 22235255, 2012). "During the experimental infection of macaques with CHIKV, we observed an early induction of IFN-α, MCP-1/CCL-2, and IL-6, followed by the detection of MIP-1α/CCL-3 and MIP-1β/CCL-4, IFN-γ, and TNF-α." (PMID 22479654, 2012). "As the X4LAI.04 infection of the ODN M362-treated tissues progressed, secretion of CCL4 and CXCL12 decreased and on day 9 p.i. became 30% lower (p = 0.047) than that produced by matched X4LAI.04-infected ligand-untreated tissues." (PMID 20862220, 2010). "In X4LAI.04 infected tissues treated with flagellin, there was a significant increase in the levels of CCL3, CCL4, and CXCL10 (by 130%, 60%, and 30%, respectively; p<0.047, n = 6) already on day 3 post-infection." (PMID 20862220, 2010).
infection (continued). "We also report here a small transient increase in CCL4 and CCL5 mRNA one day post L. major inoculation at the site of infection in C57BL/6 mice, but CCL3 clearly showed a much higher level of transcriptional induction in these mice." (PMID 20140197, 2010). "In contrast, in X4LAI.04-infected tissues production of CCL3, CCL4, CCL5, CXCL10, and CXCL12 was significantly increased compared with that in uninfected tissues and reached a maximum 5 to 9 days post-infection." (PMID 20862220, 2010). "One study has found that infection with SHIV can lead to decreased levels of CCL3, CCL4, and CCL5 in PBMCs during the acute phase of infection." (PMID 19149556, 2009). "Virally, stimulatedpDC produces chemokines, such as CCL3 (MIP-1a), CCL4 (MIP-1b), CCL5 (RANTES),CXCL8 (IL-8), and CXCL10 (IP-10) which stimulate Th1, and NK cells homing tosite of infection through IP-10 and CCL4, respectively." (PMID 19190769, 2008). "These levels were significantly lower (p<0.005 for CCL3; p<0.05 for CCL4 and CCL5) than those prior to infection." (PMID 17684570, 2007). "Protein levels of CCL4, IL-1β, and TNF-α correlated with expression of the interferon signaling module in BECs with increased protein levels after RV-16 infection correlating with increased expression post-infection." (PMID 41332562, 2025). "Moreover, infection with SFV/IFNγ and SFV/TNFα upregulated the amount of IL-6, CCL4 and CXCL11 (p < 0.05)." (PMID 40547518, 2025). "In the case of MHV-JHM infection, changes in expression (from 0% to 100%) were visible in IL-6, IL-18, IL-33, ENA-78 (CXCL5), GRO alpha (CXCL1), IP-10 (CXCL10), MCP-1 (CCL2), MIP-1 beta (CCL4), MIP-2 alpha (CXCL2), RANTES (CCL5), and TNF alpha." (PMID 40358160, 2025). "Moreover, only S- and S/N-immunized animals had reduced levels of CCL2, CCL3, CCL4 and CXCL10 chemokines after the infection compared to the PBS group." (PMID 41306976, 2025). "Secreted IL-1β, CCL4, IFN-α and IFN-γ were increased by Th17 priming of BECs prior to infection." (PMID 41332562, 2025). "In the striatum, we also see clustering within the fentanyl-treated groups based on infection status: EcoHIV-infected mice treated with fentanyl had higher concentrations of CCL2, CCL4, CCL5, and CCL11 but lower levels of CCL3 and CXCL10 than the uninfected, fentanyl-treated animals." (PMID 40447886, 2025). "Ccl4 was upregulated by SFV/Luc, but reduced with SFV/IFNγ infection." (PMID 40547518, 2025). "Additionally, CCL3, CCL4, and CXCL2 levels were low at day 14 and recovered by day 28 post-infection, also in agreement with our findings." (PMID 39044282, 2024). "Similarly, we observed significant increases in IL-17, G-CSF, CXCL1, CCL2, CCL3, CCL4, and CCL11 production in 5-LO−/− mice, compared to C57BL/6 mice, at day 7 post-infection." (PMID 39082787, 2024). "Similar to WT STm infection, genes involved in the regulation of immune responses (ATF3, BATF3, ETS2, IRF9, NFκB2, MAFA, TNFAIP3), effector functions, (CCL4, CD200L, CD40, CD72, CD80, IL18) and TLR signaling, (EAF2, TLR15, TRAF3IP2, TOLLIP) were upregulated after ΔprgH STm infection in both models." (PMID 37854334, 2023). "Infection with these bacterial or protozoan strains delays neutrophil apoptosis, resulting in an increased lifespan of up to 2–3 days, in which they release the monocyte attractant MIP-1β/CCL4." (PMID 37566060, 2023). "Additionally, CCL signaling pathways were involved in cell interaction between CD8+ Trm cells and other cells, with Ccl4-Ccr5 and Ccl5-Ccr5 ligand/receptor pairs being important between CD8+ Trm and other memory subsets after infection and reinfection." (PMID 37415817, 2023). "Compared to virulent MERS-CoV-MA-WT and MERS-CoV-MA-mNLS infection, attenuated MERS-CoV-MA-Δ4b induced, either at 4 or 6 dpi, lower levels of CCL2, CCL4 and CXCL10, which are monocyte and macrophage chemoattractants, and CXCL1 and CXCL2, which are neutrophil chemoattractants." (PMID 36129908, 2022).